DYRK1A (dual specificity tyrosine phosphorylation regulated kinase 1A)
Diseases named in the same sentence as DYRK1A in open-access papers (continued):
Sharing a sentence is not in itself a finding about the gene and the disease.
cancer (110 papers, 2013 to 2026). A tumor composed of atypical neoplastic, often pleomorphic cells that invade other tissues. "In silico screening of Broad’s Cancer Dependency Map (DepMap) showed that cancer cell line dependency scores were linked to DYRK1A gene expression (P < 0.0001 by linear regression)." (PMID 40490510, 2025). "Dual-specificity tyrosine-phosphorylation-regulated kinase1A (DYRK1A)is implicated in several human diseases, including DYRK1A syndrome,cancer, and neurodegenerative disorders such as Alzheimer’sdisease, making it a relevant therapeutic target." (PMID 40317470, 2025). "Another potent Dyrk1A inhibitor, harmol, demonstrated anti-proliferative action and caused apoptosis in various cancer cell models." (PMID 38893153, 2024). "Amongst DYRK family, DYRK1A is the most extensively studied kinase and has been associated with cancer and neurological diseases, such as Down’s syndrome (DS) and neurodegenerative diseases." (PMID 33860868, 2021). "The first indications of a role for DYRK1A in cell immortalization were obtained in studies on oncogenic viruses, indicating that DYRK1A potentially affects cell transformation in oncovirus-associated cancer models." (PMID 32751160, 2020). "Moving forward, it will be crucial to elucidate the details of this mechanism to better understand DYRK1A’s contribution to DNA damage repair and cancer susceptibilities." (PMID 31024071, 2019). "A second gene in the region, DYRK1A, is more consistently amplified and has been implicated in multiple signalling pathways contributing to cell growth and survival and cancer." (PMID 30816328, 2019). "Given strong association of the FAM117 family proteins with DYRK1A, their role as downstream effectors or possibly the regulators of DYRK1A function needs to be further investigated using the appropriate animal models of neurological development and cancer." (PMID 37900285, 2023). "In addition to mediating tumour growth, DYRK1A is also involved in the regulation of several cellular processes associated with cancer progression, such as cancer stemness maintenance and cancer cell invasion." (PMID 35655269, 2022). "Additionally, tumors with high DYRK1A level have been shown to have more potential of recurrence, which is associated with cancer stemness." (PMID 35454940, 2022). "Alterations in dosage of DYRK1A leads to defects in neurogenesis, cell growth, and differentiation, and may increase the risk of certain cancers." (PMID 34117217, 2021). "Dyrk1A has received particular attention because of its involvement not only in DS but also in several types of cancer, in which this kinase has been implicated in proliferation enhancement and reduction of cell death providing resistance to proapoptotic stimuli by chemotherapy or radiotherapy." (PMID 34090874, 2021). "In addition to neurodegenerative diseases, DYRK1A has also been reported to be associated with cancers and metabolic diseases." (PMID 27483355, 2016). "Given that the chronic conditions caused by high expression of DYRK1A, such as DS and AD, would require a long-term treatment with DYRK1A inhibitor drugs, it will be essential to evaluate the safety of these drugs given the emerging role of this kinase in cancer." (PMID 37900285, 2023). "Finally, DYRK1A could also modulate cancer risk by interacting with oncogenic viral proteins that target cell cycle regulators, such as Adenovirus E1A protein, high-risk HPV16/18 E7 proteins as well as cutaneous HPV E6 proteins." (PMID 37900285, 2023). "DYRK1A inhibitors have a high therapeutic potential for pharmacological intervention in diabetes mellitus, neurodegenerative diseases, and cancer." (PMID 40733180, 2025). "Analysis of the Broad Institute’s Cancer Cell Line Encyclopedia (CCLE) revealed that DYRK1A was overexpressed in hematopoietic malignancies, especially in BCP-ALL, relative to other tumor types." (PMID 40695793, 2025).
cancer (continued). "Recent studies in cancer models have revealed that aberrant DYRK1A activity can drive tumor progression and metastasis and that its inhibition significantly suppresses cancer growth in preclinical models." (PMID 40723805, 2025). "DYRK1A-mediated aberrant activation of the AKT pathway plays a crucial role in drug sensitivity during cancer treatment." (PMID 38590646, 2024). "Numerous studies have reported that Dyrk1A, Dyrk1B, and Clk1 are overexpressed in multiple cancers, suggesting a role in malignant disease." (PMID 38893153, 2024). "Studies have shown that dual-specificity tyrosine phosphorylation-regulated kinase 1A (DYRK1A) is a potential cancer therapeutic target, as it regulates the cell cycle by influencing the expression of oncogenes and tumor suppressor genes." (PMID 38590646, 2024). "At the same time, we also found that blocking DYRK1A expression or activity releases cells from quiescence, enforcing cancer cells to enter G1/S." (PMID 38839871, 2024). "Recently, Dyrk1A and Dyrk1B have been evaluated as therapeutic targets for neurodegenerative diseases and cancer, respectively." (PMID 38675189, 2024). "As shown in, DYRK1A gene silencing strongly reduced the percentage of quiescent cancer cells (G0), while promoting cancer cells progression through the cell cycle in both colon and TNBC cells." (PMID 38839871, 2024). "Overall, the current evidence regarding the regulation of DYRK1B expression presents several unresolved questions, specifically regarding the diverging expression patterns of DYRK1B and DYRK1A among various human cancers." (PMID 39397076, 2024). "DYRK1B appears to play a more important role in cancer cell quiescence than DYRK1A, as evidenced by its overexpression or copy number variations in human tumour samples." (PMID 39397076, 2024). "DYRK1B is the closest paralog of DYRK1A within the family, sharing a high degree of homology at the primary and secondary structure, with activities connected mostly to cancer development." (PMID 39405283, 2024). "Collectively these results show that depletion/inhibition of DYRK1A leads to increased expression of G1/S cell cycle activators, further releasing cancer cells from quiescence and promoting their progression into cell cycle." (PMID 38839871, 2024). "It would be intriguing to explore, in various cancer models, how Dyrk1a dosage affects cancer development and progression." (PMID 38255007, 2024). "DYRK1A has also been proposed as a pharmacological target for neurodegenerative disorders, diabetes and cancer." (PMID 38254631, 2023). "In contrast, its overexpression increases phosphorylation and activity of both TSC1 and TSC2, whereas increased phosphorylation of S6K1 and 4E-BP1 is observed in DYRK1A knockdown cancer cells—the effect inhibited by the mTOR-inhibiting drug rapamycin." (PMID 36982355, 2023). "Recent data support the targeting of DYRK1A for cancer therapy and to increase the tumor sensitivity to other cancer treatments." (PMID 37900285, 2023). "Since high expression of B-Myb is oncogenic and serves as clinical marker of poor prognosis in breast and other cancers, further mechanistic studies of its effect on the DYRK1A substrate LIN52 are justified." (PMID 37900285, 2023). "Although all DYRKs have been involved in different diseases, including congenital malformations, cancer, and virus infection, different lines of evidence suggest that DYRK1A and DYRK2 are the most relevant forms for human disease." (PMID 36161154, 2022). "DYRK1A can exert tumor-suppressive activities in cancer and was found to regulate cancer-related key pathways, such as apoptosis, DNA damage, activation of receptor tyrosine kinase and angiogenesis." (PMID 35454940, 2022). "Given its multifaceted role in various cancer-related biological processes, there has been significant interest in DYRK1A as a potential therapeutic target." (PMID 36362284, 2022).
cancer (continued). "Although DYRK1A was found to have a low expression in CRC compared to normal tissues, cancer samples with high DYRK1A expression were found to be enriched in late metastasis and lymph node stage." (PMID 35454940, 2022). "Particularly, inhibitors of DYRK1A are of interest for the treatment of EGFR-dependent cancer through the suppression of the cancer cells growing in EGFR-dependent tumors." (PMID 36186578, 2022). "Appreciating these nuances of DYRK1A activity will be critical for the future pursuit of DYRK1A focused cancer therapeutics." (PMID 36012629, 2022). "In several human cancer cell lines, DYRK1A has been shown to act as a caspase-9 Thr125 kinase, inhibiting intrinsic apoptotic pathways." (PMID 35053488, 2022). "In cancer, aberrant DYRK1A expression and activity plays a critical role in the progression of multiple tumours." (PMID 33924599, 2021). "Surprisingly, perhaps, most of the reports on DYRK1A in the cancer literature describe the development and use of DYRK1A inhibitors as anti-cancer therapeutics, and report that increased DYRK1A activity in cancer drives oncogenesis." (PMID 34335466, 2021). "Previous studies have suggested both oncogenic and tumour-suppressive roles for DYRK1A in cancer development and progression." (PMID 33860868, 2021). "Previous studies have demonstrated that DYRK1A/B inhibition can increase the sensitivity of quiescent cancer cells to genotoxic drugs such as cisplatin and gemcitabine." (PMID 34708541, 2021). "The search for inhibitors of the DYRK family kinases has been focused on DYRK1A due to its more established role in cancer and neurological conditions." (PMID 33842469, 2021). "Inhibition of DYRK1A with harmine reverses resistance to multiple anti-cancer drugs including mitoxantrone, camptothecin, and AZD929119,20." (PMID 32587776, 2020). "The antitumor role of DYRK1A was suggested to be related to the lower incidence of cancer in DS individuals, deviating from that observed in the normal population." (PMID 32751160, 2020). "Along similar lines, several studies have ascribed opposite functions to DYRK1A in cancer, reflecting a very complex scenario." (PMID 32751160, 2020). "Our results reveal a new role for DYRK1A in DNA damage repair, with potential implications for radioresistance and tumor suppressive mechanisms in cancer." (PMID 31024071, 2019). "The dual-specificity tyrosine phosphorylation-regulated kinase-1A (DYRK1A) functions as both a tumor-suppressing and oncogenic factor in various cancers." (PMID 31391206, 2019). "DYRK1A is considered a potential cancer therapeutic target, but the role of DYRK1A in NSCLC oncogenesis and treatment requires further investigation." (PMID 31454149, 2019). "Taken together these studies indicate that DYRK1A plays a significant role in mediating survival of cancer cells." (PMID 27796319, 2016). "In that sense, CX-4945, a newly identified inhibitor of DYRK1A, would hold promise because its safety has been already proven in phase I clinical trials for use as a cancer therapeutic." (PMID 27483355, 2016). "DYRK1A is involved in the progression of cancer by modulating several pathways related to proliferation and migration." (PMID 27483355, 2016). "DYRK1B is a paralogous kinase closely related with DYRK1A (85% identical amino acids in the catalytic domain) and is overexpressed in certain cancer types, where it favours the arrest of cells in a quiescent state to allow cellular repair." (PMID 26192590, 2015). "Furthermore, DYRK1A-mediated mTORC1 signaling in cDC1s positively correlated with effector T cell responses across multiple human cancers." (PMID 42024470, 2026). "Recent studies have suggested that the “inhibition of DREAM complex formation” in certain cancer types may enhance anticancer effects by reactivating quiescent cancer cells, such as through DYRK1A inhibitor treatment." (PMID 39796178, 2025).
cancer (continued). "However, in recent years, growing evidence has revealed that DYRK1A is also involved in various aspects of cancer biology, with context-dependent roles." (PMID 40723805, 2025). "The inconsistency of the model to predict DYRK1A perturbation in certain cancer cells could be due to the type of cancer cell studied, where DYRK1A has been reported to be an oncogene." (PMID 40901489, 2025). "Notably, we observed that DYRK1A inhibition reduces H3K4me3 levels in hippocampal neurons, which contrasts with recent findings in cancer cells, showing an increase in H3K4me3 levels upon DYRK1A inhibition." (PMID 40390093, 2025). "Noteworthy, it has been previously reported that Dyrk1A/Clk1 co-inhibition increased the efficacy of pre-mRNA splicing modulation, which could correct the abnormal splicing examined in cancer." (PMID 38893153, 2024). "Collectively, the strategy of targeting Dyrk1A, Dyrk1B, and Clk1 simultaneously with a small molecule could offer significant benefits in tackling the complex nature of cancer." (PMID 38893153, 2024). "Having shown that DYRK1A inhibition prolongate G1/S phase of the cell cycle, this suggests that DYRK1A inhibition could sensitize cancer cells to chemotherapy drugs that target cells in G1/S phase." (PMID 38839871, 2024). "Another study demonstrated a novel mechanism connecting DyrK1A/B function with autophagy in cancer." (PMID 38675189, 2024). "The function of DYRK1A in cancer has remained multifaceted and controversial." (PMID 38839871, 2024). "Altogether, these results support our hypothesis that DYRK1A gene silencing and/or pharmacological inhibition decrease cell quiescence, leading to accumulation of cancer cells in G1/S, preventing/delaying cells to enter G2/M." (PMID 38839871, 2024). "Having found that DYRK1A inhibition increases the number of cancer cells in the G1/S phase of the cell cycle, suggesting that DYRK1A inhibition may enhance the efficiency of chemotherapy drugs that act in G1/S." (PMID 38839871, 2024). "Furthermore, Dyrk1A plays an important role in cell survival by phosphorylating caspase 9 at Thr-125 to increase cancer cell survival by blocking apoptosis." (PMID 38893153, 2024). "Furthermore, we show that accumulation of cancer cells in G1/S upon DYRK1A inhibition led to significant potentiation of G1/S targeting chemotherapy drug responses in vitro and in vivo." (PMID 38839871, 2024). "Interestingly, DYRK1A protein levels were maximum in cancer cells in G0/G1 and significantly decreased as cells progressed throughout the S and G2/M phases of the cell cycle." (PMID 38839871, 2024). "We also show that releasing cancer cells from their quiescent state through inhibition of DYRK1A activity or expression resulted in cancer cells accumulation in G1/S phase, further delaying their progression to the G2/M phase, consistent with reduced cell growth." (PMID 38839871, 2024). "Indeed, several promising DYRK1A inhibitor drugs are currently in development for treatment of neurodegeneration, diabetes, and cancer." (PMID 37900285, 2023). "In quiescence, the DYRK1A protein kinase is activated, DYRK1A phosphorylates cyclin D (promotes proliferation) and p27 (inhibits proliferation)—among other targets—degrading the former and stabilizing the latter, which contributes to cancer dormancy." (PMID 37760529, 2023). "The dual role of DYRK1A in cancer could be due to its requirement for maintaining the quiescent or dormant state, which is important for cancer cell survival under the genotoxic stress conditions, such as chemotherapy [for recent review, see]." (PMID 37900285, 2023). "Therefore, the role of DYRK1A in the cancer treatment response and resistance needs to be further studied using clinically relevant tumor models and rationally designed drug treatment regimens." (PMID 37900285, 2023).
cancer (continued). "We focused our efforts on characterization of the S phase NER defect caused by lack of Dyrk1A, a kinase which regulates multiple cellular pathways implicated in neurogenesis, transcription, cell cycle control, and cancer development." (PMID 37301510, 2023). "Interestingly, although overexpression of DYRK1A inhibits proliferation of many cancer cell lines, the HEK 293T cells that express Simian Virus 40 (SV40) LT antigen and E1A proteins are resistant to this effect." (PMID 37900285, 2023). "DYRK1A has been reported to promote cell proliferation and tumour growth in several cancer types." (PMID 35655269, 2022). "Additionally, we demonstrated that the harmine-targeted suppression of DYRK1A used in conjunction with radiotherapy increases DNA double-strand breaks (DSBs) and impairs homologous repair (HR), resulting in more cancer cell death." (PMID 35053488, 2022). "Furthermore, it has been suggested that targeting DYRK1A is a potential strategy for treating cancer." (PMID 35655269, 2022). "Finally, we find that Harmine, a DYRK1A/B inhibitor, partially decreases the number of quiescent and infiltrating cancer cells." (PMID 35970913, 2022). "DYRK1A over-expression leads to cell cycle disturbance, cancer progression, and increased aggressiveness, so that DYRK1A could be an appealing drug target in chemotherapy." (PMID 34707995, 2021). "However, the role of DYRK1A in cancer is not fully understood, and both oncogenic and tumour suppressive roles for DYRK1A have been reported." (PMID 33863878, 2021). "Reducing the activity of DYRK1A in cancer cells might be a new way to attack cancers that have developed an innate resistance to pro-apoptotic stimuli." (PMID 34707995, 2021). "Given that RTKs are common targets in cancer therapy, the inhibition of DYRK1A (and its paralog DYRK1B) could be considered an element in combinatorial therapies to simultaneously target several deregulated RTKs." (PMID 32751160, 2020). "Mcl-1 overexpression confers acquired resistance to Bcl-2 inhibitors, and therefore we hypothesized that DYRK1A overexpression would also hinder the anti-cancer effects of Bcl-2 inhibitors." (PMID 32587776, 2020). "Our previous work has demonstrated that DYRK1A positively regulates EGFR/Met via regulating the expression and activation of STAT3, and that suppression of DYRK1A enhances the anti-cancer activity of EGFR-TKIs in wild-type EGFR NSCLC cells via inhibiting the STAT3 signaling pathway." (PMID 32587776, 2020). "We speculate that DYRK1A expression could be used to predict response to radiation therapy in specific cancers." (PMID 31024071, 2019). "We showed that DYRK1A repression could enhance the anti‐cancer effect of AZD9291 by inducing apoptosis and suppressing cell proliferation in EGFR wild‐type NSCLC cells." (PMID 31454149, 2019). "Collectively, our study demonstrated that DYRK1A could positively regulate the STAT3/EGFR/Met axis and DYRK1A suppression could enhance the anti‐cancer activity of AZD9291 via STAT3 pathway in EGFR wild‐type NSCLC cells." (PMID 31454149, 2019). "Therefore, targeting DYRK1A would be broadly applicable as a therapeutic approach towards at least some types of cancers and metabolic diseases." (PMID 27483355, 2016). "In virus–induced cancers, Dyrk1A may play a role as an important anti-apoptotic factor, as has been demonstrated in HPV16–immortalized keratinocytes and cervical lesions." (PMID 24676346, 2014). "In addition, Dyrk1A maintains cancer cells in a quiescence state through the formation of the DREAM complex, which maintains cells in a noncycling G0 phase by stabilizing p27Kip1, a cyclin-dependent kinase (CDK) inhibitor, and finally through inducing the degradation of cyclin D isoforms." (PMID 38893153, 2024). "Furthermore, since the DREAM complex represses the transcription of many genes with function in the DNA damage signaling and repair pathways, DYRK1A could have an impact on the efficacy of anti-cancer treatments targeting these pathways." (PMID 37900285, 2023).